MST1 (macrophage stimulating 1)
Diseases named in the same sentence as MST1 in open-access papers (continued):
Sharing a sentence is not in itself a finding about the gene and the disease.
cancer (continued). "Canonical signaling through the Hippo pathway core components (MST1/2, LATS1/2, YAP and TAZ) is important for development and tissue homeostasis while aberrant signaling through the Hippo pathway has been implicated in multiple pathologies, including cancer." (PMID 29597279, 2018). "Previous report demonstrated that MST1 was one of the substrates of CK1ε and that CK1ε might mediate Hippo signaling pathway in cancer progression and development." (PMID 29795381, 2018). "Furthermore, our study provides mechanistic insight into how MST1 levels are decreased in aggressive cancers." (PMID 27555231, 2016). "However, how cancer cells override the negative regulation induced by MST1, LATS2, MOB1, and SAV1 to exhibit constitutively inactivated Hippo signaling and activated YAP/TAZ remains puzzling." (PMID 26561204, 2015). "As a major downstream target of the Hippo/MST1 pathway, YAP2 (Yes-associated protein 2) functions as a transcriptional cofactor that has been implicated in many biological processes, including organ size control and cancer development." (PMID 21909427, 2011). "To improve the clinical benefits of PARPi, we found that targeting STRIPAK to recover or even enhance MST1/2 kinase activity could induce the development of DNA repair defects, regardless of the intrinsic DNA repair machinery, and therefore resensitize cancer cells to PARP inhibition." (PMID 35290241, 2022). "Interestingly, the core MST1/2-LATS1/2 kinase module functions as a tumor suppressor in transgenic and knockout mouse models, and no somatic mutation in these genes has been discovered in human cancer to date." (PMID 31100975, 2019). "Overall, understanding how Mst1/2 transmit signals to discrete biological processes in different cell types might allow for the development of better drug therapies for the treatments of cancers and immune-related diseases." (PMID 29459865, 2018). "However, the precise mechanisms by which MST1/2 activity is regulated in cancers remain unclear." (PMID 40019375, 2025). "Although the Hippo pathway has been implicated in human cancers, mutations or deletions of the pathway components, such as the MST1/2 or LATS1/2 kinases, are rarely detected in cancers." (PMID 38746415, 2025). "Low expression of MST1 in PDAC inhibits the activity of caspase-1, which is responsible for cancer cell pyroptosis, and thus promotes PDAC development." (PMID 40707469, 2025). "Our findings are also relevant to human disease since we found a marked MST1 activation and SIRT3 reduction in myocardial specimens of patients with cancer treated with DOX-based therapy a few years earlier." (PMID 37566283, 2023). "Loss of expression of RASSF1A in A375 is due to DNA methylation of the gene promotor, and the expression of MST1/2 and LATS1/2 in cancer also can be regulated by DNA methylation." (PMID 36038253, 2022). "As a key node in the YAP/Hippo pathway, MST1/2 are phosphorylated in an FGFR4 kinase activity-dependent manner, resulting in the proliferation and metastasis of cancer cells." (PMID 35562334, 2022). "Compared with WT cells, MST1/2-DKO cells consistently displayed a hyperactive DNA repair ability, and MST1/2 DKO strongly protected cancer cells from etoposide-induced cell death." (PMID 35290241, 2022). "Firstly, WNT inhibition restored MST-1 expression in PANC-1, contributing to the cancer suppression via ROS production." (PMID 31277479, 2019). "Several authors have noted promoter hypermethylation of MST1, MST2, LATS1, and LATS2 in various cancers." (PMID 30167083, 2018). "In contrast, our recent results demonstrated that Hsp70 decreases Mst1 activity through promoting Mst1 degradation via a CHIP dependent pathway, thereby preventing cancer cells from cisplatin induced apoptosis." (PMID 23527007, 2013).
cancer (continued). "By enhancing the activity of MST1/2 kinase to modulate the Hippo signaling pathway, EM2 effectively inhibits the proliferation of NSCLC, while simultaneously inducing apoptosis and senescence in these cancer cells." (PMID 41144784, 2026). "In summary, this study not only reaffirms MST1/2 as a viable therapeutic target for NSCLC but also provides compelling experimental evidence supporting EM2 as a highly effective and promising anti‐cancer agent." (PMID 41144784, 2026). "The expression of several Hippo kinases upstream of YAP, such as MST1, MOB1 and NF2, have been reported to be reduced in PDAC cancer tissues, which indicates that these kinases may function in PDAC progression and maintenance." (PMID 40707469, 2025). "We found that MST1, LATS1, and LATS2 were consistently expressed at low levels in the cytoplasm of basal cells of the normal epithelium, dysplastic cells of the OED, and cancer cells." (PMID 38444414, 2024). "Drugs targeting MST1, ITPKA, CD274 were mainly designed to treat cancers." (PMID 36857861, 2023). "Finally, we found a significant upregulation of MST1 and downregulation of SIRT3 levels in human myocardial tissue of cancer patients treated with DOX." (PMID 37566283, 2023). "Further, to understand the role of YAP/TAZ in PFKFB3 mediated regression of cancer stemness and ABCG2 expression, XMU-MP-1 (an inhibitor that activates YAP/TAZ via MST1/2 inhibition) used to activate YAP/TAZ in H1048CSC and H1882CSC cells and when treated with PFK158." (PMID 35804016, 2022). "We analyzed data from The Cancer Genome Atlas (TCGA) Pan-Cancer (PanCan) datasets and found a significant positive correlation between MST1R and MST1 expression in all available cancer type datasets except liver hepatocellular carcinoma (LIHC), where MST1R/MST1 are negatively correlated." (PMID 35626096, 2022). "Many previous studies have demonstrated that MST1/2 and STRIPAK scaffolds are aberrantly expressed in different types of cancers, hence MST1/2 and STRN3 dysregulation may result in the development of various cancer." (PMID 32867200, 2020). "Wilkinson et al110 found that MST1/2 can phosphorylate LC3 and promoted cell autophagy, while decreased MST1 could constrain autophagy and thereby enhance cancer cell chemo‐sensitivity." (PMID 32779318, 2020). "However, methylation-mediated epigenetic mechanisms contribute to downregulation of LATS1/2, MST1/2, and its regulator RASSF1 in some cancer types." (PMID 31100975, 2019). "The development of BRAFV600Etransgenic mice with the MST1 knockout background showed that these mice had abundant foci of poorly differentiated carcinomas and large areas without follicular architecture or colloid formation." (PMID 21249150, 2011). "Similarly to MST1, the roles of LATS in hematologic malignancies are still controversial and may depend on the types of cancer." (PMID 38368446, 2024). "In this study, we found that different cancer cell lines exhibited different activation levels of MST1/2 at HCD with extensive cell-cell contacts, suggesting a more complicated regulatory mechanism of MST1/2 from the upstream signals induced by HCD-related cell contact in mammals." (PMID 37843276, 2023). "A YAP-related signaling pathway could be proposed as part of the inflammatory cascade to develop new anti-inflammatory or anti-viral drugs that affect the upstream kinase activity of YAP, including MST1/2 and LATS1/2, which would be beneficial for the treatment of cancer and inflammatory diseases." (PMID 37397250, 2023). "As such, the MST1/2 kinases are better recruited into and inactivated by the STRIPAK complex, which relieves the inhibitory effect of MST1/2 on ZMYND8 recruitment to DSBs, thereby allowing for efficient DSB repair and endowing cancer cells with resistance to radio- and chemotherapy." (PMID 35290241, 2022).
cancer (continued). "In addition to restraining cancer cell proliferation, here we also showed that SHAP-induced recovery of MST1/2 kinase activity could suppress DSB repair and resensitize GC cells to PARP inhibition." (PMID 35290241, 2022). "Inspired by the SHAP-induced resensitization of cancer cells to PARPi, we further explored the possibility of targeting the STRIPAK assembly to induce defects in DNA repair, specifically by activating the MST1/2 kinases, which would induce synthetic lethality when combined with PARPi." (PMID 35290241, 2022). "However, Mst1/2 and Lats1/2 kinases are tumor suppressive, and their activity is low in many cancer types, unlike most oncogenic kinases, such as Src, Abl, Raf, and Akt, which are activated by mutations and involved in tumorigenesis." (PMID 28035075, 2017). "However, how MST1/2, LATS1/2, SAV1, and MOB1 are simultaneously repressed to exhibit constitutively activated YAP/TAZ in cancer remains unclear." (PMID 26561204, 2015). "Here, we report that PP2A Bβ interacts with LATS1 rather than MST1 or YAP in human placental tissues, PHTs, and HTR8/SVneo cells, which has been proposed in cancer research." (PMID 36250210, 2022). "SIRPγ serves as a negative upstream regulator of the MST1/LATS1 axis to promote YAP activation and cancer organoid growth." (PMID 35229723, 2022).
infection (22 papers, 2010 to 2026). The state of being infected such as from the introduction of a foreign agent such as serum, vaccine, antigenic substance or organism. "Clinically, individuals with mutations in the MST1 gene which encodes one of the Hippo kinases experience recurrent infection." (PMID 38624208, 2024). "Humans with loss-of-function mutations in the MST1 gene have clinical histories of recurrent infections and pneumonia." (PMID 38624208, 2024). "Clinically, a premature termination mutation in Mst1 is correlated with increased rates of infection, including some caused by S. aureus." (PMID 29490278, 2018). "Loss of the Mst-Nrf2 signaling for maintaining redox homeostasis in macrophages may be partially responsible for the recurrent infections occurred in both Mst1-deficient humans and mice." (PMID 30765703, 2019). "Intriguingly, pathogens hijack this host pathway during infection, but the role of MST1/2 in innate immune cells against pathogens is unclear." (PMID 38624208, 2024). "In this study, we demonstrate that macrophage MST1 functions as an inhibitor of inflammation and fibrosis following infection with Schistosoma japonicum (S. japonicum)." (PMID 39700261, 2024). "Over the 72-hour infection period, Lp02∆flaA had moderate intracellular growth in WT macrophages but grew robustly in Mst1/2–/– macrophages, suggesting that MST1 and MST2 are required to restrict replication of L. pneumophila." (PMID 38624208, 2024). "The results from the infection experiments demonstrate the critical role of MST1/2 in anti-bacterial host defense, showing a correlation with the increased susceptibility to infection observed in humans with MST1 deficiency and Mst1/2 double knockout mice." (PMID 38624208, 2024). "One possible explanation is that the functions of MST1 are compensated for by other genes in the ΔMst1 deletion mutant during infection of insects." (PMID 34904861, 2021). "Compared to the control group, the infection of HCMV significantly reduced the mRNA expression of Mst1, Mst2, SAV, Lats1, Lats2, Mob1, YAP1, TAZ, TEAD1-4 genes and YAP protein expression in the Hippo-YAP pathway." (PMID 34717661, 2021). "Infection with FV and additional stimulation with recombinant activated MST1 led to a further increase in the number of erythroblasts." (PMID 29222473, 2017). "Further, knock down of MST1/2 by Stk4/Stk3 siRNA in RAW264.7 and THP1 macrophages also led to a significant loss in infection-driven IRF3 activation." (PMID 27883091, 2016). "Altogether, these results clearly suggest infection-induced MST1/2 interaction-dependent activation of IRF3." (PMID 27883091, 2016). "Future studies might focus on how MST1 influences cytokine production and other immune mediators, as well as its effects on tissue structure and function during infection.." (PMID 39700261, 2024). "Mst1/2–/– macrophages fail to limit infections by E. coli, P. aeruginosa, and L. pneumophila." (PMID 38624208, 2024). "Mst1−/−Mst2fl/fl Vav–Cre mice often contract pneumonia, lung abscess, and multiple infections." (PMID 37941053, 2023). "In the case of Escherichia coli or Listeria monocytogenes infections, the number of bacteria engulfed by BMDM or neutrophils with Mst1/2 deletion is lower than in wild-type cells, and the number of bacteria retained in the cells at the later stage of infection is significantly higher." (PMID 37941053, 2023). "We then asked whether Piezo1-dependent calcium influx induces the activation of Mst1/2-Rac1 axis during the infection." (PMID 34112781, 2021). "Genes like B2m, Mst1, Igsf1, Ifitm3 and Nt5c2 were found to be upregulated whereas genes like Fyb, Ilf3, Wnt4 and Socs3 were found to be downregulated in the brain against both V3000 and V3034 infections." (PMID 28446152, 2017). "Mst1 was upregulated in spleen during V3000 and V3034 infection and therefore, likely may contribute positively towards VEEV replication in the brain and spleen." (PMID 28446152, 2017).
infection (continued). "Given that humans with MST1 deficiency experience recurrent infection, we sought to determine whether a lack of MST1/2 reduces macrophages’ ability to restrict invading bacteria." (PMID 38624208, 2024). "During SARS-CoV-2 infection, activation of the Hippo pathway contributes to the host's antiviral response, and inhibition of upstream kinases MST1/2 and LATS1 enhances viral replication, indicating its protective role against infection." (PMID 40919176, 2025). "We further validated the role of the Hippo pathway in pulmonary epithelial cells during Pm infection using XMU-MP-1 (XMU), a Hippo pathway inhibitor that reduces the activity of Mst1/2." (PMID 38493147, 2024). "In this study, it was seen that phosphorylation of MST1/2, LAST1/2 and YAP were reduced, and YAP molecule was also translocated into the nucleus with CV-A10 infection time." (PMID 38641810, 2024). "In this work, we found that mir-243 is involved in the response of C. elegans to infection with both pathogens, P. aeruginosa PAO1 and S. enterica MST1." (PMID 32963007, 2020). "To knock down MST1 protein expression, we used AAV to infect the whole brain and Western blotting to measure the infection and knockdown efficiency." (PMID 30018671, 2018). "We challenged the iBMDMs with the Gram-negative bacterial pathogen Legionella pneumophila to determine whether MST1 and MST2 affect host cytokine release during infection." (PMID 38624208, 2024). "Therefore, to explore the role of the immediate target of MST1/2 i.e. LATS1 in inducing the expression of chemokines, kinase dead form of LATS1/2 was over expressed in macrophages followed by infection with Mtb." (PMID 27883091, 2016). "Recent studies show that upstream Hippo kinases such as MST1/2 and LATS1/2 often support antiviral responses, whereas YAP and TAZ can suppress innate immune signalling and may be exploited by viruses to promote infection." (PMID 42275403, 2026). "MST1 is not involved in infection of insects by M. robertsii." (PMID 34904861, 2021). "However, RNAi of the MST1 gene resulted in significantly higher CRE signaling levels regardless of infection." (PMID 22606348, 2012). "In contrast to Mst1−/−Mst2fl/fl Vav–Cre mice, Mst1fl/flMst2fl/fl Lyz2–Cre mice (with Mst1 and Mst2 conditionally knocked out in myeloid cells) that were raised under standard SPF (specific pathogen-free) conditions for 7 months did not exhibit inflammation or infection." (PMID 37941053, 2023).
bacterial infection (10 papers, 2012 to 2024). "In phagocytes with Mst1/2 deletion, the production of ROS and mROS induced by bacterial infection is markedly deficient, which leads to a decline in bacterial killing efficiency." (PMID 37941053, 2023). "For instance, the induction of mitochondria trafficking and reactive oxygen species (ROS) is impaired in Mst1/2 deficient phagocytes after bacterial infection." (PMID 36199358, 2022). "Depletion of MST1/2 in myeloid cells leads to more susceptibility of mice to bacterial infection and severe inflammation." (PMID 31225446, 2017). "To further elucidate the individual role of MST1/2 in restricting bacterial infection, we challenged WT, Mst1/2–/–, Mst1+, or Mst2+ iBMDMs with Escherichia coli and performed a gentamicin protection assay." (PMID 38624208, 2024). "When bacterial infection or antimicrobial inflammatory response was already intense enough, the effect of MST1/2 inhibition on inflammation would be weakened." (PMID 38250155, 2024). "After recognizing bacterial infection, TLRs activated MST1/2, which phosphorylated PKC-α and activated PKC-α-LyGDI (Rho-specific guanine nucleotide dissociation inhibitor)-Rac axis, promoting assembly of the TRAF6-ECSIT complex and ROS production." (PMID 32174922, 2020). "Upon bacterial infection, MST1/2 are activated by TLR1/2/4−MyD88 signaling and in turn phosphorylates PKC-α at Ser226 and Thr228, leading to PKC-α activation." (PMID 31225446, 2017). "Consistent with its inhibitory role in pro-inflammatory response and positive role in IFN response, MST1 guards mice from chronic inflammation-driven HCC upon LPS stimulation or bacterial infection." (PMID 31225446, 2017). "Thus, the regulatory role of MST1/2 in inflammatory diseases suggests that drugs that target MST1/2 should be developed to assist antibiotics in the treatment of macrophage-related inflammatory diseases, especially drug-resistant bacterial infections." (PMID 38250155, 2024). "MST1- and MST2- deficient mice exhibited enhanced susceptibility to bacterial infection." (PMID 32174922, 2020). "Mechanistically, in the context of bacterial infection, TLR signaling activates MST1/2 which further leads to activation of the GTPase Rac, assembly of a TRAF6-ECSIT complex and mitochondrial trafficking/juxtaposition with the phagosome." (PMID 29597279, 2018). "In particular, compared with WT mice, mice without MST1/2 exhibited more sensitive inflammatory response for LPS or bacterial infection, promoted macrophage polarization to M1, and enhanced the clearance rate to LPS-modified bacteria." (PMID 38250155, 2024). "Furthermore, Mst1/2 is crucial for macrophages to induce high ROS levels during bacterial infections, but macrophages lacking Mst1/2 exhibit significantly higher ROS levels than wild-type cells." (PMID 37941053, 2023).
neurodegenerative disease (5 papers, 2014 to 2025). A disorder of the central nervous system characterized by gradual and progressive loss of neural tissue and neurologic function. "Although increases in MST1/2 have been implicated in other neurodegenerative diseases and cause neuronal death the pathogenic role of MST1/2 has not been elucidated in HD." (PMID 30054496, 2018). "MST1 has been shown to be involved in other neurodegenerative diseases." (PMID 25183307, 2014). "Hyper-activation of the pathway components such as MST1 and the consequent inhibition of YAP have been noted in several neurodegenerative disease models." (PMID 40178516, 2025).
cardiovascular diseases (4 papers, 2018 to 2025). "Targeting Mst1 represents a promising avenue for the development of novel therapies for cardiovascular diseases associated with myocardial injury." (PMID 39006833, 2024). "Mst1, a downstream factor of the Hippo pathway, has been implicated in acute and chronic cardiovascular disorders." (PMID 29760744, 2018). "Extensive research has investigated the involvement of Mst1 in diverse cardiovascular diseases, positioning it as a potential therapeutic target." (PMID 39006833, 2024). "The Mst1/Hippo signaling pathway, a critical regulator of cellular processes, has emerged as a potential therapeutic target in cardiovascular diseases." (PMID 39006833, 2024). "Convincing experimental data show the harmful effect of Mst1 on cardiovascular disease." (PMID 29760744, 2018). "Targeting MST1 and MSP pathways could provide novel therapeutic avenues for both cardiovascular diseases and cancer, supporting the multifaceted role of melatonin in human health." (PMID 41282233, 2025).